IGF1 (insulin like growth factor 1)
Diseases named in the same sentence as IGF1 in open-access papers (continued):
Sharing a sentence is not in itself a finding about the gene and the disease.
Insulin resistance (continued). "Although more studies are needed to support these observations, our results indicate that it may be the case that some AD-like degu recapitulate some Igf1 gene regulatory features seen in aging, insulin resistance and AD pathogenesis." (PMID 35860672, 2022). "In addition, the insulin-like growth factor 1 (IGF-1) was found decreased in patients with insulin resistance, and showed an important role on skeletal muscle mass." (PMID 35565832, 2022). "When insulin resistance occurs, insulin or IGF-1 signaling is inhibited." (PMID 35846289, 2022). "The increased incidence is thought to be secondary to insulin resistance and the increase in IGF-1." (PMID 35326592, 2022). "In agreement, inducible liver insulin receptor knockout mice (iLIRKO), a model of severe hepatic insulin resistance, shows significant beta-cell mass enhancement in parallel to elevated levels of hepatic and circulating insulin-like growth factor-1 (IGF-1), a known trophic factor for beta cells." (PMID 35053251, 2022). "In addition, insulin resistance promotes the secretion of Insulin-like growth factor 1 (IGF-1), which also results in axial elongation." (PMID 35333875, 2022). "In fact, IGF-1 levels were correlated to the level of hepatic insulin resistance." (PMID 35053251, 2022). "In addition, reduced HDL-C levels are closely related to insulin resistance, which leads to consecutive activation of insulin-like growth factor-1 (IGF-1) signaling that exhibits mitogenic activity via the PI3K/Akt cascade and RAS/RAF/MAPK/ERK pathway." (PMID 35884921, 2022). "PA could also improve insulin-resistance and interfere with the levels of various circulating tumor-promoting proteins such as insulin-like growth factor-1." (PMID 35205684, 2022). "Insulin resistance promotes the overproduction of IGF-1 and IGF-2 due to the limitation of IGFBP." (PMID 36003786, 2022). "Insulin resistance and hyperinsulinemia are important features of diabetes and growing in vitro evidence suggests a direct effect of insulin and insulin-like growth factor 1 (IGF-1) on endometrial cancer." (PMID 35439978, 2022). "Mechanistically, insulin resistance and the resultant hyperinsulinemia promotes endometrial carcinogenesis and progression by the direct pro-proliferative and anti-apoptotic effect of insulin and insulin growth factor (IGF-1) on endometrial cells." (PMID 35600348, 2022). "Accordingly, genetic variants that primarily reduce GH secretion and signaling would lead to reduced IGF-1 bioactivity but without the consequent effects of elevated GH on fatty acid metabolism and insulin resistance and, hence, no alteration in T2D risk." (PMID 36530175, 2022). "Furthermore, the higher the adiposity, the more insulin resistance and hyperinsulinemia, which in turn increase the levels of IGF1 and BC cell proliferation." (PMID 35538143, 2022). "Our analysis showed that some of the pathways activated predominantly at the 4 h time point in HG conditions have direct roles in mediating blood glucose homeostasis and have been implicated in insulin resistance, particularly PAK1, HGF, BMP and IGF-1 signaling pathways." (PMID 36463298, 2022). "Thus, it is assumed that not only insulin signaling but also IGF-1 signaling are impaired in patients with insulin resistance." (PMID 36198696, 2022). "These dysfunctions include (i) insulin resistance and an increase in insulin-like growth factor 1, (ii) elevated adipokines secreted from visceral adipocytes, and (iii) free fatty acids and aromatase activity; these all collectively attribute to MetS and furthermore NAFLD." (PMID 36661654, 2022). "Insulin resistance and hyperinsulinemia stimulate the release of insulin-like growth factor 1 (IGF-1) and IRS-1, mediating signals for cell proliferation and inhibition of apoptosis and might contribute to the development of HCC." (PMID 36612019, 2022).
Insulin resistance (continued). "This study aims to investigate the correlation of insulin-like growth factor-1 (IGF-1) levels as an anabolic factor, myostatin levels, and insulin resistance as catabolic factors with sarcopenia in the pathogenesis of sarcopenia in elderly patients undergoing hemodialysis." (PMID 35371569, 2022). "Whilst hyperammonemia, inflammation and alcohol may drive sarcopenia progression in chronic liver disease, other systemic factors including insulin resistance, decreased testosterone and IGF-1 may influence sarcopenia progression." (PMID 35406665, 2022). "These inflammatory cytokines may also decrease the anabolic effect of insulin-like growth factor-1 and promote insulin resistance." (PMID 35407455, 2022). "Insulin growth factor-1 (IGF1) is a hormonal regulator of insulin resistance in diabetes." (PMID 34683087, 2021). "Fasting glucose and insulin levels, as well as glycated haemoglobin (HbA1c), insulin-like growth factor (IGF-1), the homeostatic model assessment for insulin resistance (HOMA) and the quantitative insulin sensitivity check index (QUICKI) did not change significantly." (PMID 34117276, 2021). "Hyperglycemia, insulin resistance, elevated insulin and insulin-like growth factor-1 (IGF-1) levels, inflammatory cytokines, dyslipidemia, increased leptin, and decreased adiponectin have been attributed to the increased risk of cancer in patients with diabetes." (PMID 34830886, 2021). "However, the inhibition of insulin/IGF-1 signaling impairs cellular glucose uptake and enhances the generation of insulin resistance." (PMID 34476533, 2021). "Patients who responded optimally to the approach significantly improved glycaemic control, insulin resistance, and reduced IGF-1 availability, controlling and reducing the serum concentration of markers associated with increased risk of Barrett’s esophagus evolution towards adenocarcinoma." (PMID 34684639, 2021). "IGF-1 SDS was negatively associated with insulin resistance in obese prepubertal boys, independent of other traditional cardiovascular disease risk markers." (PMID 34485526, 2021). "While IGF-1 has insulin-agonistic actions and has been used for treatment of severe insulin resistance, IGF-1 reduction with the GH antagonist pegvisomant improves glycemic control in acromegalic patients with diabetes or impaired glucose tolerance despite elevated GH." (PMID 33995272, 2021). "Hyperinsulinemia resulting from insulin resistance may increase the bioavailability of insulin-like growth factor (IGF)-1 by lowering IGF-binding proteins, and both insulin and IGF-1 can stimulate the growth of GCa." (PMID 34356646, 2021). "In addition, higher intakes of fiber and phytochemicals reduce inflammation, circulating estrogens and androgens hormones, insulin resistance, and Insulin-like Growth Factor-1 concentration play a key role in cancer prevention." (PMID 34750430, 2021). "The mechanism by which long-term DM may affect the incidence of PCa is hypothesized to be related to increased insulin-like growth factor 1 (IGF-1) levels, hyperglycaemia, insulin resistance and compensatory hyperinsulinemia." (PMID 33924591, 2021). "The elevation of IGF-1 is usually considered to be a sign of obesity and insulin resistance." (PMID 34901103, 2021). "Male: ↑systolic blood pressure, hyperglycemia, hypertriglyceridemia, insulin resistance and serum igf1 concentrations; ↑lipid peroxidation and catalase activity; rehabilitation reversed the effects female: less sensitive to the metabolic effects of zinc restriction." (PMID 34746215, 2021). "As a matter of fact, insulin-like growth factor-1 (IGF-1) and IGF-1 receptor expression are known to be associated with increasing risk for breast cancer, and both factors are promoted by hyperinsulinemia and insulin resistance." (PMID 34594472, 2021).
Insulin resistance (continued). "Based on the results, we can infer that the correlation between IGF-1 and traditional cardiovascular disease may be mediated by insulin resistance; thus, it represents a possible direction for a forthcoming research and therapeutic approach." (PMID 34485526, 2021). "Low insulin-like growth factor 1 (IGF-1) levels have been proven to be associated with many traditional cardiovascular risk factors, but it still remains controversial with the relationship between IGF-1 and insulin resistance." (PMID 34485526, 2021). "In addition, insulin-like growth factor 1 (IGF1) / insulin-like growth factor 1 receptor (IGF1R) signaling pathway has been demonstrated to be essential for the process of insulin resistance, which leading to metabolic diseases and type 2 diabetes." (PMID 34527673, 2021). "The decrease in circulating molecules such as adiponectin and IGF-1 during sleep restriction could contribute to the establishment of brain insulin resistance while FFAs could also worsen systemic insulin resistance." (PMID 34539357, 2021). "The roles of IL-6, TNF- α, CRP, and IGF-1 in insulin resistance have been widely studied." (PMID 33432036, 2021). "The positive pleiotropy may be partially explained by the association between both cancers and pulmonary obstruction (i.e., decreasing FEV1/FVC), as well as higher HbA1c and lower IGF-1 levels, both of which indicate insulin resistance." (PMID 33579919, 2021). "IGF-1 overexpression was suggested in the past as a modulator of SMA severity in mice, the finding that insulin resistance is associated with IGF-1 levels raised concerns that insulin resistance may attenuate the IGF-1 myotrophic effect." (PMID 34371910, 2021). "Regarding the molecular mechanism underlying the progression of sarcopenia in the SDT group, disruption to insulin/IGF-1-Akt signaling due to insulin resistance and low serum IGF-1 levels was considered to provoke abnormalities in muscle strength and mass in the SDT group." (PMID 32405506, 2020). "Experimental studies showed that insulin resistance could lead to compensatory hyperinsulinemia, which enhanced the cross-binding of insulin to the insulin-like growth factor-1 (IGF-1) receptors expressed on breast epithelial cells." (PMID 32015762, 2020). "We therefore believe that, in conditions of insulin resistance and hyperinsulinemia, prolonged exposure to high insulin might induce not only β-cell insulin resistance, but also resistance to IGF-1, which could contribute to β-cell failure in T2D." (PMID 32150819, 2020). "The association in human literature between IGF-1 and insulin resistance is more conflicting but seem to exist in non-diabetic patients with sleep apnea." (PMID 32655494, 2020). "Moreover, it mediates insulin resistance by direct modulation of Insulin Like Growth Factor 1 (IGF-1)." (PMID 33424775, 2020). "Another shortcoming is that we could not investigate whether there is a U- or J-shaped relationship between IGF-1 levels and cardiometabolic diseases and insulin resistance, as suggested by a few observational studies." (PMID 32548700, 2020). "In conclusion, in this exploratory study to elucidate possible mechanism underlying the U-shaped relationship of IGF-1 with CVD, we demonstrated that higher IGF-1 levels are beneficial for body composition but seem to be detrimental with respect to insulin resistance." (PMID 33633687, 2020). "Adipose tissue-derived inflammation also promotes insulin resistance in glucose storage tissues that can lead to hyperinsulinemia, and insulin and insulin-like growth factors (IGF) such as IGF-1 have pro-mitogenic and anti-apoptotic effects that are cancer promotive." (PMID 33327948, 2020). "Insulin resistance may result from increased production of GH in this model as a compensatory mechanism for reduced feedback inhibition by IGF-1." (PMID 31732912, 2020).
Insulin resistance (continued). "Thus, in this study, the poor ‘brown response’, insulin resistance, and decreased serum level of IGF-1 were likely related to the reduced bone mass in mice lacking irisin." (PMID 33060792, 2020). "A limitation of the study is the overlapping effects of both higher GH doses and higher IGF-1 level which could have influenced the results, for instance with respect to dose-dependent effect of GH on insulin resistance." (PMID 33633687, 2020). "When taken together, our results suggest that hyperinsulinemia and insulin resistance play a role in the development of acrochordon at tissue receptor level, and could be mediated by IGF–1." (PMID 33143702, 2020). "Disturbances in IGF1 levels such as that we observed may be an indication of reduced sensitivity of tissues to IGF1, so called IGF1 resistance, which often accompanies insulin resistance in DM273." (PMID 31515486, 2019). "Insulin resistance which is common in obesity and leads to an increase in the level of IGF-1." (PMID 31231120, 2019). "Prevailing theory has been that the elevations of circulating IGF-1 and insulin levels in insulin resistance and type 2 diabetes are both partly responsible for the acceleration of VSMC proliferation and restenosis causing stent failure in the treatment for coronary artery disease." (PMID 31562314, 2019). "This risk may arouse from special diabetic pathology, such as hyperglycemia, hyperinsulinemia, insulin resistance, distorted insulin-like growth factor-1 (IGF-1) pathway, oxidative stress, enhanced inflammatory processes, and aberrant sex hormone production." (PMID 31337431, 2019). "Several large longitudinal studies have investigated links between serum IGF-1 and risk of type 2 diabetes mellitus (T2DM), and have found evidence for an association between increased incidence of insulin resistance and T2DM in subjects with either low-normal or high-normal IGF-1 levels." (PMID 31416218, 2019). "It includes the emergence of insulin resistance, other than variations in the insulin-like growth factor-1 (IGF-1)/IGF-1 receptor (IGF-1R) axis, occurrence of adipocytokine imbalance, the state of chronic tissue inflammation, and the induction of cellular oxidative stress." (PMID 32063842, 2019). "Hyperinsulinemia and increased insulin-like growth factor 1 (IGF-1), which is a result of insulin resistance, is another hypothesis for thyroid carcinogenesis." (PMID 30733504, 2019). "Higher insulin resistance may result in a lower ratio of IGF-1/IGFBP-3 in HCV-related CLD patients with severe steatosis." (PMID 29342898, 2018). "Zn deficiency may contribute to higher serum ferritin levels and lower IGF-1/IGFBP-3 ratios, surrogate measures for circulating free IGF-1 levels, and thus substantially exacerbate the insulin resistance in such patients." (PMID 29342898, 2018). "However, supplementation with GH and IGF-1 can have dissimilar effects, particularly in modulating insulin resistance, adipose tissue function and lipid metabolism in the liver." (PMID 29724029, 2018). "Given the synergistic effect of hypoxia and insulin resistance in liver fibrosis, previous study showed that hypoxia leads to a decrease in PPARγ expression, followed by inhibition of IR transcription, resulting in the blockade of IGF-1 and subsequent signals." (PMID 29686697, 2018). "Insulin resistance in PCOS women increases the levels of free bioavailability of IGF-1 and may contribute to abnormalities in ovarian steroidogenesis." (PMID 30775682, 2018). "In patients with insulin resistance, the hyperinsulinemia may enhance the bioavailability of IGF-1 and IGF-2 by inhibiting the production of the IGFBP-1 and IGFBP-2 in the liver." (PMID 29495350, 2018). "It was presumed that the insulin resistance in patients with diabetes mellitus leads to a chronic hyperinsulinemic state and elevation of insulin-like growth factor-1 levels; this plays a crucial role in the cell proliferation and finally in the occurrence of CRC." (PMID 30486335, 2018).
Insulin resistance (continued). "Additionally, serum IGF-1 levels have been found to increase in parallel with the transient rise in insulin resistance that occurs during pubertal development." (PMID 30622975, 2018). "Altogether, these data provide evidences that insulin signaling and/or IGF-1 signaling disruption at multiple levels may result into the alteration of insulin metabolic effects, thus contributing to insulin resistance and T2D." (PMID 30469501, 2018). "In a recent cross-sectional study, performed on Chinese nondiabetic obese children and adolescents, low serum IGF-1 levels have been associated with insulin resistance, dyslipidemia, obesity, and the presence of metabolic syndrome." (PMID 29036907, 2017). "The putative role of IGF-1 in the insulin resistance observed in OSA was also examined." (PMID 28384333, 2017). "However, the direct relationship between IGF-1 and insulin resistance in skeletal muscle peripheral tissues is still unclear." (PMID 28654680, 2017). "Although GH induces insulin resistance and raises glucose, in the clinical setting, IGF-1 may represent a better marker of the metabolic burden of acromegaly; this point is echoed in other national cohort analyses." (PMID 28733467, 2017). "In addition, administration of recombinant IGF-1 increases glucose uptake, and improves glucose tolerance in patients with type 2 diabetes and severe forms of insulin resistance." (PMID 28881681, 2017). "In type 2 diabetic patients, increased insulin resistance and resulting hyperinsulinemia might upregulate the production of insulin-like growth factor-1 (IGF-1) and insulin receptor subtrate-1 (IRS-1)." (PMID 28333991, 2017). "Lower circulating IGF-1 levels have been associated with IGT/T2DM, and insulin resistance." (PMID 28881681, 2017). "Increased serine phosphorylation of IRS1 could provide a novel mechanism to explain the insulin resistance reported in bGH mice and could play a role in inhibiting excess IGF-1 signaling in the gastrocnemius." (PMID 28870245, 2017). "This link was hypothesized to be through increased insulin-like growth factor 1 (IGF-I) levels and bioavailability seen with high insulin resistance." (PMID 28819564, 2017). "What's more, obese women may suffer from insulin resistance, and concurrent hyperinsulinemia with excess insulin-like growth factor-1 receptor (IGF-1) could additionally induce androgen steroidogenesis and lead to tumor development." (PMID 27119509, 2016). "Decreased IGF-1 and HDL-C levels have been reported to be associated with insulin resistance." (PMID 27343122, 2016). "Here, we tested the hypothesis that central IGF‐1 is uniquely capable of restoring whole‐body insulin action in a model of age‐related insulin resistance and declining IGF‐1 levels." (PMID 26534869, 2016). "Insulin resistance, chronic inflammation, oxidative damage, and dyslipidemia are generally characterized by the activation of the IRS1/PI3K/AKT pathway, particularly, this being the route activated by insulin or insulin-like growth factor 1 (IGF-1) in insulin resistance." (PMID 26999118, 2016). "In addition, exogenous IGF-1 administration has been shown to reduce serum glucose levels, not only in healthy individuals, but also in those with insulin resistance, type I, and T2D." (PMID 26733412, 2016). "Growth hormone (GH) signaling stimulates the production of IGF‐1; however, increased GH signaling may induce insulin resistance and can reduce life expectancy in both mice and humans." (PMID 26990883, 2016). "Indeed, it has been reported that during cachexia, both cancer patients and mouse models, experience a decrease in the circulating levels of the anabolic factor insulin-like growth factor-1 (IGF-1) and the development of insulin resistance." (PMID 26900952, 2016).